LAG3 (lymphocyte activating 3)
Diseases named in the same sentence as LAG3 in open-access papers (continued):
Sharing a sentence is not in itself a finding about the gene and the disease.
Arthritis (6 papers, 2019 to 2025). Inflammation of a joint. "We and others have shown that low LAG‐3 levels, particularly on T cells and monocytes, are associated with increased disease activity in arthritis and other inflammatory diseases." (PMID 40788332, 2025). "Genes commonly associated with T cell activation, such as LAG3, CCL5, ITM2A, CCR5, and CD2, were highly expressed in SF, in comparison to PB T cells of arthritis patients." (PMID 38254179, 2024). "In CIA mice, LAG3+ B cell frequencies were also decreased and negatively correlated with the CIA arthritis score." (PMID 37143367, 2023).
asthma (6 papers, 2019 to 2026). "In a mouse model of asthma, the adoptive transfer of LAG3+ Treg-of B cells inhibited Th2 cytokine secretion and eosinophilic inflammation and ameliorated asthma symptoms." (PMID 36865540, 2023). "It has been shown that T regulatory type 1 (Tr1) cells express high level of LAG-3 for cell contact-mediated immune suppression during asthma." (PMID 36865540, 2023). "Lag3-deficient DNT cells showed weak MHC-II recognition and therapeutic effects on OVA-induced asthma." (PMID 31534137, 2019). "Here the authors show, using mouse model of adoptive cell transfer, that CD4-CD8- T cells can suppress the function of dendritic cells and T follicular helper cells via Lag3 to provide allergen-specific protection from asthma." (PMID 31534137, 2019). "Since IL-17 is a known marker of lung inflammation and asthma severity, these data could imply the importance of expanding lung levels of LAG3+ Treg in asthmatic lung as the levels of LAG3+cTreg or LAG3+uTreg on the inflamed lung tissues were both correlated with lower serum level of IL-17." (PMID 36067164, 2022). "The expression levels of CD28, CD59, LAG3, TCRab and TIGIT were higher, while CD45, CD45RO, RORγ, OX40 and Tbet lower in cluster 16 in acute pneumonia, stable pneumonia, acute asthma and stable asthma." (PMID 34841705, 2021).
Cirrhosis (6 papers, 2020 to 2025). A chronic disorder of the liver in which liver tissue becomes scarred and is partially replaced by regenerative nodules and fibrotic tissue resulting in loss of liver function. "High pre-TACE serum LAG-3 level was positively associated with more cirrhosis pattern, advanced BCLC stage, pre-TACE alanine aminotransferase (ALT) level, and pre-TACE aspartate aminotransferase (AST) level." (PMID 34691076, 2021). "High pre-TACE serum LAG-3 level was found to correlate with a more cirrhosis pattern (P= 0.034), high pre-TACE AST levels (P=0.020), high pre-TACE ALT levels (P=0.029), and advanced BCLC stage (P=0.017)." (PMID 34691076, 2021). "Using the stratification cut-off points as in the assessment of tumor response, we found that high levels of LAG-3 were positively correlated with unfavorable clinical parameters, such as advanced tumor stage, more cirrhosis pattern and degree of hepatic damage." (PMID 34691076, 2021). "The proportion of Treg and CD8 T cell-LAG3 (Exhausted CD8 T cell) enhanced, while the proportion of CD8 T cell-TNF (effector CD8 T cells) decreased from cirrhosis to HCC." (PMID 38116005, 2023). "We also found that the levels of LAG-3+cells and CD8+ T cells, HbsAg, cirrhosis, tumor size and tumor number were independent predictors of DFS." (PMID 32762721, 2020). "Multivariate analysis revealed that expression of LAG-3+cells and CD8+ T cell, cirrhosis, vascular invasion and tumor size were independent prognostic factors for OS." (PMID 32762721, 2020).
Hepatitis (6 papers, 2013 to 2026). Inflammation of the liver. "PubMed/MEDLINE, EMBASE, and CENTRAL databases were searched in July 2023 based on keywords including ICIs (anti–Programmed cell death protein 1/Programmed Death-Ligand 1, anti–CTLA–4, and anti-LAG3) and hepatitis." (PMID 39298568, 2024). "This is reflected in the OVA_X_CreERT2_X_OT-I model by high frequencies of OT-I cells expressing the co-inhibitory receptors PD-1 and LAG-3, even after recovery from hepatitis and antigen clearance." (PMID 23869228, 2013). "Among these, randomized controlled trials demonstrated that adding LAG-3 or TIGIT inhibitors to established therapies did not increase the risk of elevated hepatic enzyme levels or hepatitis." (PMID 41660625, 2026). "In this study, we review the current understanding of immune inhibitory receptors such as PD-1, CTLA-4, CD244, Lymphocyte activation gene 3 (LAG-3), T cell immunoglobulin domain and mucin domain-3 (Tim-3), and CD160 (expressed on virus-specific T cells in hepatitis)." (PMID 28703774, 2017).
pancreatic ductal adenocarcinoma (6 papers, 2019 to 2026). An infiltrating adenocarcinoma that arises from the epithelial cells of the pancreas. "FOXP3+RORγt+ Tregs were increased in PBMC from patients with pancreatic ductal adenocarcinoma, and they produced IL-17A and expressed high level of LAG3." (PMID 31354747, 2019). "One biological process in which this protein might be involved is the suppression of T cell-mediated lysis: Galectin-3 was shown to interact with LAG3 present on CD8 cells in pancreatic ductal adenocarcinoma." (PMID 34503258, 2021). "In pancreatic ductal adenocarcinoma (PDAC), MET reduced LAG3 and STAT3 levels, and increased overall survival." (PMID 40520013, 2025).
pneumonia (6 papers, 2020 to 2024). An acute, acute and chronic, or chronic inflammation focally or diffusely affecting the lung parenchyma, caused by an infection in one or both of the lungs (by bacteria, viruses, fungi, or mycoplasma.). "In vivo studies further demonstrate that LAG-3 blockade weakens the protective role of Tregs in lethal pneumonia, indicating that LAG-3 plays a crucial role in mediating maximal inhibitory effects." (PMID 39743998, 2024). "In our current study, we identified DNT and CD4+ TCM expressed increased Lag3 and Tim3 in acute pneumonia and stable pneumonia." (PMID 34841705, 2021). "Clusters 09 and 16, which identified to be DNT and CD4+ TCM, respectively, significantly increased in patients with acute pneumonia and stable pneumonia with an enhanced expression of Lag3 and Tim3, which were identified to be the exhausted clusters." (PMID 34841705, 2021). "The LAG-3 inhibitor relatlimab reported fewer AEs, including pyrexia and pneumonia." (PMID 39051335, 2024). "The expression levels of CD59, CD28, CCR7, CD270, Tim3, Eomes, lymphocyte activation gene‐3 (LAG3), TCRab and TIGIT were higher, while that of OX40, CD45RO, PD‐L1 and CD25 lower in cluster 09 in patients with acute pneumonia." (PMID 34841705, 2021). "Of note, the top induced inhibitory immune-checkpoint was found to be LAG3 (lymphocyte-activation gene 3; syn.: CD223), dominantly induced in “DAD2” and “pneumonia” based on RNA-seq, which was also confirmed by immunohistochemistry wherein mainly lymphocytes showed strong staining signals." (PMID 35992303, 2022).
psoriasis (6 papers, 2022 to 2026). An autoimmune condition characterized by red, well-delineated plaques with silvery scales that are usually on the extensor surfaces and scalp. "Beneficial effects following LAG-3 downregulation induced by monoclonal antibodies were also observed in the treatment of psoriasis in humans." (PMID 37685876, 2023). "The proportion of Tr1 (CD49b+ LAG-3+) cells in CD3+ CD4+ T-cells in the blood of psoriasis patients was decreased in psoriasis patients compared with healthy individuals, and the proportion of Tr1 cells decreased as PASI increased." (PMID 36110854, 2022). "A study utilized spatial transcriptomics to compare the expression of inhibitory T cell ICs, specifically CTLA-4, TIGIT, LAG-3, and PDCD1 (encoding PD-1), on tissue-resident memory T cells in patients with dermatomyositis (Th1-driven) and psoriasis (Th17-driven)." (PMID 38817600, 2024). "IL-10 plays a prominent role in establishing tolerance in SLE, RA, psoriasis, and celiac disease which might indicate that bona fide CD49b+LAG-3+ Tr1 cells are involved but this requires more investigation." (PMID 36389662, 2022).
rectal cancer (6 papers, 2022 to 2025). A primary or metastatic malignant neoplasm that affects the rectum. "Previous studies on esophageal and rectal cancers revealed upregulation of immune checkpoint molecules, including LAG3, after chemo-radiation." (PMID 37311986, 2023). "For example, PD-1 and LAG-3 expression increased in T cells of rectal cancer patients after RT." (PMID 41246357, 2025). "The role of LAG-3 and TIM-3 has not been extensively studied in rectal cancer." (PMID 37232754, 2023).
renal carcinoma (6 papers, 2023 to 2026). A carcinoma arising from the epithelium of the renal parenchyma or the renal pelvis. "As shown in the results, the expression levels of immune checkpoints were differential in different groups, especially PD-1, CTLA4 and LAG3, which are commonly found in renal cancer, were more significantly expressed in the high-risk group." (PMID 38546385, 2024). "Preclinical studies have shown that various solid tumors, including colorectal, ovarian, and renal cancers, are associated with LAG-3, suggesting that LAG-3 is a promising immune checkpoint for the development of immunotherapies." (PMID 37927462, 2023). "In the current study, we analyzed for the first time the distribution of LAG3 in renal cancer and renal tissue using single-cell analysis and investigated its expression, prognostic significance, immune microenvironmental relevance, and pathway enrichment using bioinformatics techniques." (PMID 38291496, 2024). "Notably, significant correlations between LAG3 expression and stage and grade were identified specifically in renal cancer." (PMID 38277212, 2024).
small cell lung carcinoma (6 papers, 2021 to 2025). Small cell lung cancer (SCLC) is a highly aggressive malignant neoplasm, accounting for 10-15% of lung cancer cases, characterized byrapid growth, and early metastasis. "LAG-3 levels are significantly overexpressed in both small cell lung cancer (SCLC) as well as in NSCLC." (PMID 37509517, 2023).
thyroid cancer (6 papers, 2020 to 2024). "In contrast, LAG3 mRNA was expressed at a lower level in tumors than in normal tissues, and higher LAG3 mRNA levels were associated with a better prognosis in liver and thyroid cancer." (PMID 38062416, 2023). "We found an increase in the frequency of PD-1+ and LAG3+ B cells in the plasma of HNSCC patients as compared to healthy individuals, which parallels findings from studies of hepatocellular and thyroid cancer patients." (PMID 32751214, 2020).
urothelial carcinoma (6 papers, 2022 to 2024). A malignant neoplasm derived from the transitional epithelium of the urinary tract (urinary bladder, ureter, urethra, or renal pelvis). "Interestingly, LAG3, which we found to be upregulated specifically on CD8+ T cells after immunotherapy, was associated with the response to anti-PD-1 immunotherapy within the tumors of patients with urothelial carcinoma." (PMID 38275874, 2024). "T cells widely expressed PD-1, while LAG3, TIM3, OX40, and 4-1BB were expressed at relatively low levels, which indicates that targeting these molecules in urothelial carcinoma may be less effective than targeting PD-1." (PMID 35725444, 2022).
allergic asthma (5 papers, 2018 to 2023). A asthma with a basis in a pathological type I hypersensitivity reaction. "Activin-A has been reported to be the main cytokine for Tr1 generation and LAG-3 expression in allergic asthma." (PMID 36865540, 2023). "Indeed, elevated expression of LAG-3 in DNT cells in a murine model of allergic asthma affected MHC-II antigen recognition and thus modulated allergen-specific immune regulation by these cells." (PMID 36865540, 2023). "LAG3, an MHC-class-II-binding CD4+ homologue has been identified to suppress airway inflammation in a mouse model of OVA-induced allergic asthma." (PMID 36067164, 2022).
liver fibrosis (5 papers, 2023 to 2025). "In addition, analysis of peripheral NK cells revealed a progressive increase in the expression of NK exhaustion markers of PD-1, TIGIT, and LAG-3 with advancing stages of liver fibrosis." (PMID 40643462, 2025). "Then we speculate that immune checkpoints might correlate with HSC activation and liver fibrosis and found that SLC1A5 was significantly negatively associated with CTLA4, LAG3, and PDCD1; similarly, SLC7A5 was significantly negatively associated with CTLA4 and LAG3." (PMID 39698464, 2024). "Thus, although Egr2 might be a target for liver fibrosis in MASH, Egr2 should be targeted selectively in monocytes and macrophages in order not to inhibit protective responses by LAG3+CD4+CD25- regulatory T cells." (PMID 38831027, 2024).
lymph node metastasis (5 papers, 2020 to 2025). "Overall, UICC stadium, frequency and extent of lymph node metastasis were higher in the LAG3-positive group (p = 0.009 and 0.001, respectively)." (PMID 32232506, 2020). "The expression of SELENOP was not statistically significant concerning patient age (p > 0.05); however, differences in histological grade, lymph node metastasis, LAG-3, CD244, estrogen receptors, progesterone receptors, and Her-2 expression were statistically significant (p < 0.05)." (PMID 40821907, 2025). "Additionally, LAG3 overexpression was observed in lymph node metastasis and distant metastatic tissues when compared to normal tissues." (PMID 38277212, 2024). "However, most probably due to a correlation with pT-stage and lymph node metastasis, the LAG3 expression failed to serve as an independent prognostic marker, since the survival benefit correlated with LAG3 expression was predominantly detectable in pT3/4 tumours." (PMID 32592066, 2020).
Pleural effusion (5 papers, 2020 to 2022). The presence of an excessive amount of fluid in the pleural cavity. "In MPM, T cells in pleural effusion express inhibitory molecules such as PD-1, TIM-3, LAG-3 and have a higher diversity of TCR clones compared to blood of the same patient." (PMID 34249695, 2021).
sarcoidosis (5 papers, 2019 to 2024). Sarcoidosis is a multisystemic disorder of unknown cause characterized by the formation of immune granulomas in involved organs. "Surprisingly, lymphoid cells in non–sarcoidosis-affected skin specifically induced immune checkpoint genes, including TIGIT, LAG3, and PDCD1." (PMID 39225100, 2024). "Among T cells, we found increased levels of IL-2R+ TIGIT+ LAG3+ CD4+ T cells in IPF, increased levels of CXCR3+ CD226+ CD4+ T cells in sarcoidosis, and increased levels of PD1+ TIGIT+ CD57+ CD8+ T cells in CTD-ILDs." (PMID 36949950, 2023). "Clusters #6074, #6025, #6066, and #6054 were prevalent in sarcoidosis and characterized by CD64+ CD11blo CD14– CD223(LAG3)+ HLA-DR+ CD163hi expression." (PMID 36949950, 2023).
soft tissue sarcoma (5 papers, 2020 to 2025). A malignant neoplasm arising from muscle tissue, adipose tissue, blood vessels, fibrous tissue, or other supportive tissues excluding the bones. "For example, increased LAG-3 expression is used to stratify patients with HNSCC into high-risk groups, and a high level of LAG-3 expression in soft tissue sarcoma tissues has been found to be significantly correlated with high pathological grade and late stage." (PMID 37670328, 2023). "Existing studies have shown that in the mouse soft tissue sarcoma model, antibody blockade of LAG-3 can significantly inhibit tumor growth and increase the secretion level of IFN-γ in CD8+ cytotoxic T cells and CD4+ helper T cells." (PMID 40761795, 2025). "In soft tissue sarcoma model mice, LAG-3 blockade decreased tumor growth and enhanced the secretion of IFN-γ by CD8+ and CD4+ T cells." (PMID 37670328, 2023). "LAG-3 expression in T cells from the peripheral blood of soft tissue sarcoma patients was higher than that in healthy people." (PMID 35494015, 2022). "LAG-3 is mainly produced and localizes to CD8+ TILs in individuals with soft tissue sarcoma." (PMID 35494015, 2022).
T cell lymphoma (5 papers, 2021 to 2022). "While they are rarely expressed on T cell lymphomas, LAG3 is expressed on CD4+ and CD8+ tumor-infiltrating lymphocytes and could be a druggable target alone or in combination with CD47." (PMID 36429020, 2022). "In addition, we show that the combination of a novel anti-LAG-3 mAb with PD-L1_1 have remarkable effects also on T cell lymphoma derived cells." (PMID 35008285, 2021). "To further confirm the binding specificity of the tribody 53G for LAG-3, we investigated also its binding on HuT 78 cell line, which is derived from CD4+ human T cell lymphoma and expresses high levels of LAG-3 receptor, but low or absent levels of PD-1 and PD-L1." (PMID 36071464, 2022). "Since CRISPR/Cas9 technology has been already explored for multiplexing editing of a combinatorial set of genomic sites in T cells, we initially tested our CRISPR/Cas9 approach for simultaneous editing of PD-1, LAG-3, and TIM-3 on the T cell lymphoma cell line EL4 and then on primary T cells." (PMID 35328630, 2022). "To further confirm the binding specificity of the tribodies for LAG-3, we investigated their binding and biological effects on the HuT78 cell line, which is derived from CD4+ human T cell lymphoma and expresses high levels of LAG-3 receptor, but low or absent levels of PD-1 and PD-L1." (PMID 35408827, 2022).
ulcerative colitis (5 papers, 2020 to 2023). An inflammatory bowel disease involving the mucosal surface of the large intestine and rectum. "In line with these previous efforts, the objective of this study was specifically to identify and quantify LAG3+ T-cells in ulcerative colitis samples with their spatial context preserved." (PMID 38066073, 2023). "This assay proved to be robust in both tissue segmentation and phenotyping, was compatible with automated workflows, and revealed presence of LAG3+ T-cells in ulcerative colitis biopsies with spatial context preserved." (PMID 38066073, 2023). "We investigated the role of LAG-3 by analysing its expression and function in immune cells from blood and tissue of patients with ulcerative colitis [UC]." (PMID 32179884, 2020). "In addition, LAG3 expression was found at similar frequencies on all subsets of T helper cells, including Th1, Th17, Th1/Th17, and Th0/2 cells, and on memory T cells in patients with ulcerative colitis." (PMID 37172058, 2023). "Functional studies of Lag-3 in human Tregs report only small proportions of Tregs are LAG-3 positive, although this fraction increases in inflamed tissues such as in the lamina propria of ulcerative colitis (UC) patients, and various tumors." (PMID 38283365, 2023).
co-infection (4 papers, 2022 to 2025). "In our study, a progressive increase in the expression of LAG-3 was observed at the early stage (6 to 24 hpi) of PCV2 or PRRSV single infection and co-infection with PCV2 and PRRSV in PAMs." (PMID 36992486, 2023). "Collectively, the up-regulation of both LAG-3 and TIM-3 genes within virus-infected PAMs reflects they may be involved in the regulation of immune response during PCV2 and PRRSV co-infection." (PMID 36992486, 2023). "However, at the late stage (48 hpi) of co-infection with PCV2 and PRRSV in PAMs, the LAG-3 expression level was decreased, but this did not occur after infection with PCV2 or PRRSV alone." (PMID 36992486, 2023).
depression (4 papers, 2023 to 2025). "Notably, a substantial number of upregulated genes associated with depression were identified, such as Ctss, Ifitm3, H2‐K1, Vim, Bst2, Lag3, Cd74, Isg15, Gbp3, and Cxcl10." (PMID 38946585, 2024). "Microglial Lag3 expression increases in chronic unpredictable stress-exposed mice, a model for depression, whereas electroconvulsive stimulation, a known antidepressant treatment, reduces microglial Lag3 levels." (PMID 41177809, 2025). "A recent report demonstrated that LAG-3 expression is elevated in hippocampal microglia of patients with major depression and that microglial LAG-3 is involved in the antidepressant effects of electroconvulsive therapy." (PMID 38026700, 2023).